H2AL3 (H2A.L variant histone 3)
Description:
Core component of nucleosome. Nucleosomes wrap and compact DNA into chromatin, limiting DNA accessibility to the cellular machineries which require DNA as a template. Histones thereby play a central role in transcription regulation, DNA repair, DNA replication and chromosomal stability. DNA accessibility is regulated via a complex set of post-translational modifications of histones, also called histone code, and nucleosome remodeling.
Synonyms: H2A.L.3; H2AL1RP
Gene: Protein-coding gene on chromosome X (37,994,272 to 37,994,904, forward strand). Ensembl gene ENSG00000229674.
Subcellular location: Nucleus; Chromosome
Gene Ontology:
Molecular function: structural constituent of chromatin; DNA binding; protein heterodimerization activity
Biological process: heterochromatin formation
Cellular component: nucleosome; chromosome; nucleus
Homologues: Orthologues: dog H2AL1Q (42% identical), mouse H2al2a (36% identical), mouse H2al2b (34% identical), mouse H2al2c (34% identical), rat H2al3 (32% identical), mouse H2al1n (31% identical), mouse H2al1a (30% identical), mouse H2al1b (30% identical), mouse H2al1c (30% identical), mouse H2al1d (30% identical), mouse H2al1e (30% identical), mouse H2al1f (30% identical), and 27 more. Paralogues in human: H2AL1Q (71% identical), H2AB2 (30% identical), H2AB3 (30% identical), H2AB1 (29% identical), MACROH2A2 (29% identical), H2AC1 (28% identical), H2AC21 (28% identical), H2AC6 (28% identical), H2AJ (28% identical), H2AX (28% identical), H2AC11 (28% identical), H2AC12 (28% identical), and 15 more.